RNU6-867P (RNA, U6 small nuclear 867, pseudogene)
Gene: Small nuclear RNA gene on chromosome X (76,244,968 to 76,245,074, forward strand). Ensembl gene ENSG00000201826.
Homologues: Orthologues: chimpanzee U6 (98% identical), macaque U6 (93% identical), mouse Gm25143 (81% identical), pig U6 (80% identical), dog U6 (78% identical). Paralogues in human: RNU6-166P (89% identical), RNU6-43P (87% identical), RNU6-49P (87% identical), RNU6-1158P (86% identical), RNU6-12P (86% identical), RNU6-13P (86% identical), RNU6-140P (86% identical), RNU6-21P (86% identical), RNU6-24P (86% identical), RNU6-25P (86% identical), RNU6-31P (86% identical), RNU6-32P (86% identical), and 1286 more.